LINC00960 (long independently transcribed non-coding RNA 960)
Gene: Long non-coding RNA gene on chromosome 3 (75,672,232 to 75,742,089, forward strand). Ensembl gene ENSG00000242516.
Diseases named in the same sentence as LINC00960 in open-access papers:
LINC00960 is named in the same sentence as 6 diseases in open-access papers, as found by Europe PMC text mining. Sharing a sentence is not in itself a finding about the gene and the disease. The quoted sentences say what the papers report.
bladder cancer (2 papers, 2020 to 2024). "This should be clinically applicable in that higher urinary or serum exosomal LINC00960 and LINC02470 expression levels might be associated with higher pathological grade or poorer prognosis of bladder cancer patients." (PMID 32517366, 2020). "Knockdown of LINC00960 or LINC02470 in high-grade cells reduced these aggressive traits and signaling activations in low-grade recipient cells, thus suggesting that LINC00960 and LINC02470 could be valuable biomarkers for monitoring bladder cancer progression." (PMID 39039064, 2024). "Furthermore, we identified two novel exosomal lncRNAs, LINC00960 and LINC02470, that both play pivotal roles in the EMT process and promote the aggressiveness of bladder cancer cells." (PMID 32517366, 2020). "Our findings indicate that exosome-derived LINC00960 and LINC02470 from high-grade bladder cancer cells promote the malignant behaviors of recipient low-grade bladder cancer cells and induce EMT by upregulating β-catenin signaling, Notch signaling, and Smad2/3 signaling." (PMID 32517366, 2020). "Thus, T24-Exos or J82-Exos-derived LINC00960 and LINC02470 could be important aggressiveness-promoting factors in bladder cancer progression." (PMID 32517366, 2020).
breast carcinoma (2 papers, 2024 to 2025). "While the association between LINC00960 and tumorigenicity has been documented in various cancers, our study marks the pioneering effort to unveil its expression in relation to molecular subtypes of breast cancer and elucidate its functional role in TNBC." (PMID 39039064, 2024). "Notably, the aggressive TNBC subtype exhibited heightened expression of LINC00960 based on multiple breast cancer cohorts, associated with critical cellular processes." (PMID 39039064, 2024). "For instance, our previous investigation suggested LINC00960 to promote breast cancer via the hsa-miR-34a-5p, hsa-miR-16-5p, BMI1, KRAS, and AKT3 network." (PMID 39995981, 2025). "The elevated expression of LINC00960 in TNBC compared to HR+ breast cancer was further validated in our cohort using RT-qPCR." (PMID 39039064, 2024). "Building upon current data, our investigation revealed an elevated expression of LINC00960 specifically in the basal breast cancer subtype using PAM50 classifications in the TANRIC database." (PMID 39039064, 2024). "Our findings highlight the involvement of LINC00960 in breast cancer progression by regulating multiple oncogenic networks, providing crucial insights into the molecular landscape of breast cancer in this region and beyond." (PMID 39039064, 2024). "Our findings highlight the distinct lncRNA expression patterns in breast cancer subtypes and underscore the crucial role for LINC00960 in promoting TNBC pathogenesis, suggesting its potential utilization as a prognostic marker and therapeutic target." (PMID 39039064, 2024). "Nonetheless, our study provides comprehensive lncRNA catalogue of breast cancer from the MENA region, proposing LINC00960 as a promising prognostic marker and therapeutic target, particularly for TNBCs." (PMID 39039064, 2024).
lung adenocarcinoma (1 paper, 2024). A carcinoma that arises from the lung and is characterized by the presence of malignant glandular epithelial cells. "Our findings align with prior research implicating LINC00960 in the progression of osteosarcoma, pancreatic, and lung adenocarcinoma." (PMID 39039064, 2024).
cancer (1 paper, 2024). A tumor composed of atypical neoplastic, often pleomorphic cells that invade other tissues. "Moreover, our study reveals that LINC00960, previously associated with various cancers, exhibits elevated expression in TNBC, predicting poor prognosis, which underscores its potential as a novel therapeutic target." (PMID 39039064, 2024). "Taken together, our analysis provides compelling evidence implicating LINC00960 as unfavorable prognostic biomarkers affecting several key Cancer hallmarks." (PMID 39039064, 2024). "Our research unveils the positive link between LINC00960 and numerous cancer hallmarks." (PMID 39039064, 2024). "Mechanistically, transcriptomic profiling of LINC00960-depleted cells confirmed its tumor-promoting role, likely through sponging of hsa-miR-34a-5p, hsa-miR-16-5p, and hsa-miR-183-5p, leading to the upregulation of cancer-promoting genes including BMI1, KRAS, and AKT3." (PMID 39039064, 2024). "Our study contributes valuable insights, affirming the oncogenic properties of LINC00960 in TNBC, further supported by existing literature across diverse cancer types." (PMID 39039064, 2024).
tumor (1 paper, 2024). "Further bioinformatic investigation suggested LINC00960 to promote tumor progression through sponging hsa-miR-16-5p, hsa-miR-183-5p, and hsa-miR-34a-5p." (PMID 39039064, 2024).
LINC00960 also shares sentences with these, for which no sentence is quoted: osteosarcoma (1 paper).